MC1R (melanocortin 1 receptor)
Diseases named in the same sentence as MC1R in open-access papers (continued):
Sharing a sentence is not in itself a finding about the gene and the disease.
breast carcinoma (7 papers, 2013 to 2025). "Although an association between total MC1R expression and cell proliferation was observed, studies on the variant-specific effect on breast cancer proliferation are required for an in-depth understanding." (PMID 37679505, 2023). "We explored this association in breast cancer and discovered a significant relationship between MC1R expression and disease grade and progression." (PMID 37679505, 2023). "Tumors that expressed MC1R showed significantly higher expression of Ki67, a proliferation marker, suggesting that MC1R might be associated with breast cancer cell proliferation." (PMID 37679505, 2023). "It remains unknown whether overactive MC1R or constitutive MC1R expression, by itself, are causative factors in breast cancer development." (PMID 37679505, 2023). "Our results revealed a new association between MC1R and breast cancer, which could be potentially targeted therapeutically." (PMID 37679505, 2023). "However, the detailed mechanisms underlying MC1R-induced growth in breast cancer cells need further confirmation." (PMID 37679505, 2023). "MC1R signaling accelerates G1/S phase progression and promotes breast cancer progression through the cAMP-CREB/ATF-1 and ERK-NFκB pathways." (PMID 40547309, 2025). "Based on these results, the potential use of MC1R as a prognostic marker for breast cancer should be further explored." (PMID 37679505, 2023). "Differential MC1R protein expression was observed across the TMA, indicating that MC1R is expressed in many breast cancers." (PMID 37679505, 2023). "Further, MC1R-KD breast cancer cells formed significantly fewer colonies on soft agar and significantly fewer tumors in athymic nude mice." (PMID 37679505, 2023). "To better understand the effect of MC1R in breast cancer progression, we evaluated MC1R expression in a human breast cancer tumor microarray (TMA)." (PMID 37679505, 2023). "In line with this, an analysis of MC1R mRNA expression across different breast cancer types in TCGA revealed a significantly lower MC1R expression in HER2-positive breast cancers." (PMID 37679505, 2023). "An analysis of MC1R expression in different breast cancer tissue types in TCGA revealed a significantly higher expression in breast cancer tissue compared to normal breast tissue." (PMID 37679505, 2023). "In conclusion, our results showed that active MC1R signaling contributes to breast cancer progression in vitro and in vivo." (PMID 37679505, 2023). "In contrast, our results show that MC1R activation accelerated S phase entry in breast cancer cells by promoting Cyclin D1 expression." (PMID 37679505, 2023). "To understand the impact of MC1R on breast cancer, we used T-47d and MCF7, two breast cancer cell lines that showed high MC1R expression." (PMID 37679505, 2023). "A significantly higher MC1R expression was observed in primary breast cancer (and metastatic breast cancers among the white population) compared to normal breast tissue in both the Black or African American and white populations." (PMID 37679505, 2023). "Further exploration revealed that MC1R signaling accelerates breast cancer cell proliferation and contributes to tumorigenicity, identifying it as a therapeutic target for breast and, potentially, other cancers." (PMID 37679505, 2023). "To further confirm MC1R activity in breast cancer cell lines, we generated MC1R-knock down (MC1R-KD) T-47d cells and evaluated intracellular cAMP levels and MC1R downstream signaling." (PMID 37679505, 2023). "However, we detected MC1R expression in breast cancer cell lines by western blot and in the breast cancer TMA by immunohistochemistry." (PMID 37679505, 2023). "Nevertheless, our results suggest that active MC1R signaling could accelerate breast cancer progression." (PMID 37679505, 2023). "Additionally, our analysis showed a significantly higher MC1R expression in breast cancer tissue than in adjacent normal tissue." (PMID 37679505, 2023).
breast carcinoma (continued). "Future studies on MC1R expression in different cancers, including breast cancer, must evaluate whether MC1R expression is sufficient for targeted therapy." (PMID 37679505, 2023). "These contrasting effects of MC1R activation in melanocytes and breast cancer might be due to the differences in downstream transcription factors." (PMID 37679505, 2023). "Further characterization of this new association in breast cancer revealed that MC1R promotes breast cancer cell proliferation by signaling through the MC1R-cAMP-CREB/ATF-1 and MC1R-ERK-NFκB axes, resulting in accelerated progression of the cells from the G1 to the S phase of the cell cycle." (PMID 37679505, 2023). "This suggests the potential therapeutic effect of MC1R inhibition on breast cancer." (PMID 37679505, 2023). "Additionally, since MC1R downregulation and inhibition decreased cell proliferation, MC1R inhibition should be evaluated as a potential treatment strategy for breast cancer." (PMID 37679505, 2023). "Our results also suggested that MC1R could be developed as a prognostic marker for breast cancer." (PMID 37679505, 2023). "Therefore, we examined whether active MC1R signaling is transduced through ERK in breast cancer cells." (PMID 37679505, 2023). "Mechanistically, MC1R signaling through the MC1R-cAMP-CREB/ATF-1 and MC1R-ERK-NFκB axes accelerated the G1-S transition in breast cancer cells." (PMID 37679505, 2023). "To eliminate the effects of other oncogenic pathways in breast cancer cells and to confirm the mechanisms contributing to MC1R-driven cell proliferation, we used HEK 293 T cells transiently overexpressing MC1R." (PMID 37679505, 2023). "These suggested that active MC1R signaling through two signaling pathways, the MC1R-cAMP-CREB/ATF-1 and the MC1R-ERK-NFκB pathways, controlled growth and proliferation in breast cancer cells." (PMID 37679505, 2023). "This suggested that MC1R signaling through the MC1R-cAMP-CREB/ATF-1 and MC1R-ERK-NFκB axes promotes cell cycle progression and accelerates cell proliferation in breast cancer cells." (PMID 37679505, 2023). "An analysis of breast cancer cell lines using DepMap and cBioPortal showed that T-47d and MCF7 did not carry any MC1R mutations." (PMID 37679505, 2023). "Further exploration revealed that breast cancer tissue shows a significantly higher MC1R expression than normal breast tissue, and knocking down MC1R significantly reduced cell proliferation in vitro and in vivo." (PMID 37679505, 2023). "To determine whether MC1R signaling was active in the breast cancer cell lines, T-47d and MCF7, we treated the cells with the MC1R agonist and α-MSH analog, Nle4-D-Phe7-α-MSH (NDP-MSH), or the MC1R antagonist, MSG-60629–31, and evaluated the changes in intracellular cAMP levels." (PMID 37679505, 2023).
xeroderma pigmentosum (7 papers, 2020 to 2024). Xeroderma pigmentosum (XP) is a rare genodermatosis characterized by extreme sensitivity to ultraviolet (UV)-induced changes in the skin and eyes, and multiple skin cancers. "For instance, heritable mutations such as in MC1R, CDK4, and CDKN2A, as well as genetic conditions like xeroderma pigmentosum (XP), have all been associated with an increased risk of melanoma development." (PMID 38067178, 2023).
colitis (6 papers, 2017 to 2023). Inflammation of the colon. "The authors demonstrated how MC1Re/e and, thus, an impairment in MC1R-mediated signalling resulted in a worse course of DSS-induced experimental colitis in mutated mice than in wild-type (WT) mice." (PMID 37508552, 2023). "For instance, mice with a frameshift mutation in the MC1R gene experience significantly greater colitis in response to dextran sulfate sodium (DSS) or Citrobacter rodentium (a transmissible form of murine colitis) compared with wild-type mice." (PMID 36891301, 2023). "Mice treated with alpha-MSH attenuated experimental colitis while mice deficient for the alpha-MSH receptor MC1R developed aggravated DSS-induced colitis." (PMID 31350463, 2019). "Indeed, as compared with wild-type mice, dextran sodium sulfate or Citrobacter rodentium-induced colitis significantly was aggravated in MC1R null (MC1Re/e) mice that have a frameshift mutation between exon 4 and 5 and are lacking a functional MC1R." (PMID 33716796, 2021). "Multiple lines of evidence have also demonstrated a role for the melanocortin system in colitis and suggest the potential for MC1R agonists specifically in the treatment of intestinal inflammation." (PMID 36891301, 2023). "MC1R, and the pathways it activates, has been mainly studied in experimental colitis models showing how MC1R signalling pathways impact parameters related to colitis disease activity." (PMID 37508552, 2023). "In addition, Mc1r‐null mice are less resistant to experimentally induced oxidative stress and inflammation, leading to dermal fibrosis and collagen synthesis or the aggravation of colitis (Böhm & Stegemann, 2014)." (PMID 29316344, 2018). "This highlights that there are probably MC1R-dependent and -independent mechanisms by which the KPV peptide may act therapeutically in experimental colitis." (PMID 37508552, 2023). "Interestingly, MC1R, which can be activated by alpha-MSH, ACTH, and MECO-I, has been shown to have a functional role in limiting intestinal inflammation; deletion of that receptor produces colitis." (PMID 29152323, 2017).
prostate carcinoma (6 papers, 2001 to 2025). A carcinoma that arises from epithelial cells of the prostate gland. "Polymorphisms in the MC1R gene, leading to red pigmentation, are linked to a reduced risk of prostate cancer (Weinstein, Virtamo & Albanes, 2013), and MC1R is highly expressed in esophageal squamous cell carcinoma." (PMID 40547309, 2025). "MC1R Arg160/Arg160 homozygotes were at increased risk (P = 0.027, odds ratio = 1.94) while TYR A2/A2 homozygotes were at reduced risk of prostate cancer (P = 0.033, odds ratio = 0.48)." (PMID 11720436, 2001). "We studied 210 prostate cancer cases and 155 controls to determine whether vitamin D receptor (VDR, Taql and Fokl variants), tyrosinase (TYR, codon 192 variant) and melanocortin-1 receptor (MC1R, Arg151Cys, Arg160Trp, Val92Met, Asp294His and Asp84Glu variants) genotypes are associated with risk." (PMID 11720436, 2001).
uveal melanoma (6 papers, 2002 to 2025). A melanoma derived from melanocytes of the uveal tract. "To assess the role of MC1R variants in uveal melanoma, we have analysed a cohort of 350 patients for the changes within the major region of the gene displaying sequence variation." (PMID 14612910, 2003). "We have assessed the risk of uveal melanoma associated with germline MC1R variants through sequence analysis of 350 patients and a series of 133 population controls." (PMID 14612910, 2003). "We performed this study to determine whether germline MC1R variants confer an increased risk of uveal melanoma." (PMID 14612910, 2003). "We interpret the data as indicating that MC1R variants do not appear to be major determinants of susceptibility to uveal melanoma." (PMID 14612910, 2003). "Accordingly, MC1R may constitute a valuable complementary marker for both cutaneous and uveal melanomas to be utilised in diagnosis and possibly in T cell based immunotherapy." (PMID 12177778, 2002). "Furthermore, we found that the age at diagnosis of uveal melanoma in carriers of MC1R variants was not significantly different from noncarriers." (PMID 14612910, 2003). "Our investigation was prompted by the observation that patients with uveal melanomas have a greater number of cutaneous naevi than that of the general population, and that numbers of cutaneous naevi, as well as skin and hair colour, are a function of MC1R genotype." (PMID 14612910, 2003). "The TCGA-UVM data confirmed that MC1R, MC4R, and MC5R were expressed in uveal melanoma, with MC1R exhibiting the highest expression level (data not shown)." (PMID 34436011, 2021). "In comparison, our results revealed a strong expression of MC1R in all tested primary tissue sections (n=8) (data not shown) and uveal melanoma cell lines." (PMID 12177778, 2002).
diabetes (5 papers, 2021 to 2025). "Our results demonstrated that PL-8331 therapy, a peptide that also targets MC1r and MC5r, effectively protected the eye from retinopathy associated with diabetes." (PMID 37108092, 2023). "Targeting MC1r and MC5r in the retina may be important in preventing damage and cell loss in the retina in uveitis, diabetes, and IRI." (PMID 38785932, 2024). "The possibility of targeting the MC1r and MC5r has been shown to reduce the retinopathy mediated by diabetes." (PMID 37108092, 2023). "To this regard, we have previously reported an emerging role of melanocortin receptors subtypes 1 and 5 (MC1R and MC5R), which when activated are able to counteract the retinal pro-inflammatory milieu induced by diabetes." (PMID 34603029, 2021).
erythropoietic protoporphyria (5 papers, 2022 to 2023). A rare congenital metabolic disorder characterized by an inborn error of porphyrin-heme biosynthesis. "MT‐7117 is a novel oral MC1R agonist that induces melanogenesis in vitro and in vivo, suggesting its potential application for the prevention of phototoxic reactions in patients with photodermatoses, such as erythropoietic protoporphyria and X‐linked protoporphyria." (PMID 35665216, 2022). "Dersimelagon (formerly MT‐7117) is a novel, orally administered nonpeptide small molecule selective agonist for melanocortin 1 receptor currently being investigated for the treatment of erythropoietic protoporphyria, X‐linked protoporphyria, and diffuse cutaneous systemic sclerosis (dcSSc)." (PMID 37078227, 2023). "Dersimelagon (formerly MT‐7117) is a novel, orally administered nonpeptide small molecule selective agonist for melanocortin 1 receptor currently being investigated for the treatment of erythropoietic protoporphyria, X‐linked protoporphyria, and diffuse cutaneous systemic sclerosis." (PMID 37078227, 2023). "The synthetic peptide [Nle4, D‐Phe7]‐αMSH (NDP‐αMSH), also known as afamelanotide, binds predominantly to MC1R and induces skin pigmentation that prevents phototoxic reactions and it has been approved in several countries for the treatment of adult patients with erythropoietic protoporphyria (EPP)." (PMID 35665216, 2022). "MT-7117, or dersimelagon, is a selective agonist of MC1R that has been found to have a much higher selectivity for MC1R than NDP-MSH (afamelanotide), a peptide effective in treating erythropoietic protoporphyria (EPP)." (PMID 37569558, 2023).
ovarian carcinoma (5 papers, 2002 to 2024). A malignant neoplasm originating from the surface ovarian epithelium. "The top 10 genes with most deleterious mutations in the Chinese ovarian cancer population were MC1R (12%), MLH1 (9%), PRKDC (8%), KIF1B (8%), FANCM (7%), FANCI (6%), PRSS1 (6%), SDHA (6%), BRCA2 (6%), and CFTR (5%)." (PMID 38817903, 2024). "Meanwhile, we applied fit Chi-square calculation to evaluate these mutations with ovarian cancer risk and found MC1R:c.359T>C, ERCC5:c.1586G>C and PRSS1:c.72C>T that significantly fails to conform Hardy-Weinberg equilibrium (P-value<0.05)." (PMID 38817903, 2024). "Although the present study used only a small sample size, it presents two major findings: the presence of hybrid cells in high grade ovarian cancer, as assessed by two different methods, and MC1-R as a prognostic marker for ovarian cancer." (PMID 36499015, 2022). "On the other hand, MC1-R was associated with RFS, suggesting MC1-R as a poor prognosis protein in ovarian cancer." (PMID 36499015, 2022). "Here, we describe for the first time the expression of MC1-R in CTCs from ovarian cancer patients and its correlation to poor RFS when expressed in CTM at the first and second follow-ups." (PMID 36499015, 2022). "Additional studies, maybe multicenter, are needed to more thoroughly evaluate the function of MC1-R in ovarian cancer, as well as its role as fusion marker." (PMID 36499015, 2022). "In addition, the expression of MC1-R and EpCAM in hybrid cells brings new perspectives as a possible marker for this phenomenon in ovarian cancer." (PMID 36499015, 2022). "Furthermore, the high-frequency mutated genes in the American population fell within the screening range recommended by the NCCN guidelines, while the high-frequency mutated genes, MC1R, PRKDC, and KIF1B in the Chinese ovarian cancer cohort were not covered." (PMID 38817903, 2024). "In addition, two colon carcinomas, four ovarian carcinomas, and one embryonal kidney line did not express MC1R." (PMID 12177778, 2002).
atherosclerosis (4 papers, 2021 to 2025). A disease characterized by the build-up of fatty material and calcium deposition in the arterial wall resulting in partial or complete occlusion of the arterial lumen. "We have previously observed that global deficiency of MC1-R signaling perturbs cholesterol homeostasis, increases arterial leukocyte accumulation and accelerates atherosclerosis in apolipoprotein E knockout (Apoe-/-) mice." (PMID 34868038, 2021). "To address this question, we employed bone marrow transplantation to generate a model of hematopoietic MC1-R deficiency and characterized the immunophenotype of this model in the context of atherosclerosis." (PMID 34868038, 2021). "Recently, a study investigated whether a systemic deficiency of MC1R signaling affects the development of atherosclerosis." (PMID 37569558, 2023). "However, the observed phenotype cannot be solely attributed to loss-of-function of MC1-R in leukocytes, since this receptor is distributed also in other tissues relevant to atherosclerosis such as the liver, endothelium and adipose tissue." (PMID 34868038, 2021). "Indeed, MC1-R activation was found to be protective in experimental models of atherosclerosis, but the underlying mechanism is likely to be multifactorial and extends beyond the immunoregulatory function of MC1-R." (PMID 34868038, 2021). "It is well-established that MC1-R exerts potent anti-inflammatory actions, making it an attractive therapeutic target in inflammatory diseases such as atherosclerosis." (PMID 34868038, 2021). "To determine the contribution of leukocyte MC1-R to atherosclerosis, we transplanted Apoe-/- or Apoe-/- Mc1re/e BM into lethally-irradiated Apoe-/- recipient mice." (PMID 34868038, 2021). "Owing to the multifaceted role of MC1-R in modulating inflammation, chronic activation of the receptor has been shown to provide protection against atherosclerosis in both pharmacological and genetic models." (PMID 34868038, 2021). "We recently identified a novel role for MC1-R in macrophage cholesterol transport, which provides protection against atherosclerosis by inhibiting foam cell formation." (PMID 34868038, 2021). "In recent years, MC1-R has been recognized as a promising therapeutic target in various inflammatory diseases including atherosclerosis." (PMID 34868038, 2021). "Since various cell types besides leukocytes express MC1-R, we aimed at investigating the specific contribution of leukocyte MC1-R to the development of atherosclerosis." (PMID 34868038, 2021). "The study highlighted the significant role of MC1R in the development of atherosclerosis." (PMID 37569558, 2023). "Therefore, the exact role of leukocyte MC1-R in the development of atherosclerosis remains to be determined." (PMID 34868038, 2021). "Hematopoietic MC1-R deficiency drastically increased tissue leukocyte counts in Apoe-/- mice without affecting atherosclerosis." (PMID 34868038, 2021). "The findings suggested that a lack of MC1R signaling may exacerbate atherosclerosis by disrupting cholesterol transport and increasing arterial monocyte deposition." (PMID 37569558, 2023). "Opening a completely new avenue for investigation, we found that MC1-R is also present in CD4+ T cells, which are important for immune responses during host defense and play a central role also as drivers of autoimmune diseases and chronic inflammatory diseases such as atherosclerosis." (PMID 34868038, 2021).